MMP15 (matrix metallopeptidase 15)
Diseases named in the same sentence as MMP15 in open-access papers (continued):
Sharing a sentence is not in itself a finding about the gene and the disease.
Insulin resistance (3 papers, 2012 to 2024). Increased resistance towards insulin, that is, diminished effectiveness of insulin in reducing blood glucose levels. "MMP15 has also been implicated in human obesity and insulin resistance." (PMID 37445827, 2023). "More work is required to fully unravel the exact role of MMP15 depletion in obesity and insulin resistance states." (PMID 37445827, 2023). "We can say that we are the first to evaluate MMP-15 in adipose tissue and to propose the potential relationship between it, obesity and insulin resistance." (PMID 22471305, 2012). "Finally, there is evidence that MMP15 gene expression alters in the development of insulin resistance." (PMID 38574408, 2024). "Indeed, MMP15 is significantly downregulated in both omental (OM) (~50% decrease) and ScWAT in obese patients with high- and low-insulin resistance status (~40% and ~33% decrease, respectively) compared to lean individuals." (PMID 37445827, 2023). "Down regulation of gene expression MMP-15 and its significant negative correlation with the HOMA index point to the existence of a potential relationship between this metalloproteinase, VEGF-C, VEGF-D and insulin resistance in morbidly obese subjects." (PMID 22471305, 2012).
melanoma (3 papers, 2016 to 2025). A malignant, usually aggressive tumor composed of atypical, neoplastic melanocytes. "Similarly, MMP15 and MMP16 were shown to promote invasiveness of tumor cells in 3D fibrin matrices, while, in particular, MMP16 is highly expressed in aggressive melanoma." (PMID 32575583, 2020).
Obesity (3 papers, 2012 to 2023). Accumulation of substantial excess body fat. "In order to study potential obesity effects on MMP15 in a more physiological context we considered maternal obesity as a chronic condition and also tested the effect of long‐term exposure to the obesity‐associated intrauterine environment on MMP15 in vivo levels." (PMID 32614494, 2020). "In order to test whether long‐term exposure to the obesity‐associated intrauterine environment might affect MMP15, we quantified MMP15 mRNA and protein levels in first trimester placental tissue from lean (BMI < 25, GW 5‐11, n = 24) vs obese women (BMI ≥ 30, GW 5‐10, n = 18)." (PMID 32614494, 2020). "Therefore, in the present study, we tested whether the obesity associated pro‐inflammatory environment alters MMP15." (PMID 32614494, 2020). "Thus, both in vitro as well as in vivo results strongly suggest lack of an obesity effect on placental MMP15 in first trimester human pregnancy." (PMID 32614494, 2020). "However, we cannot rule out that obesity affects any other of the complex mechanisms governing CTB invasion, independent on MMP15." (PMID 32614494, 2020).
preeclampsia (3 papers, 2012 to 2022). Preeclampsia is a hypertensive disorder of pregnancy that is characterized by new-onset hypertension with proteinuria presenting after 20 weeks of gestation, and depending on mild or severe forms may initially present with severe headache, visual disturbances, and hyperreflexia. "Next, we measured expression of MMP-15 in placenta from women with severe early-onset preeclampsia (n = 8) and gestationally matched preterm controls (n = 8)." (PMID 22768148, 2012). "We can only speculate on the possible role, if any, that MMP-15 may play in the pathogenesis of preeclampsia." (PMID 22768148, 2012). "Furthermore, as MMP15 is upregulated in preeclampsia, proper regulation of MMP15 in decidualized ESCs could be necessary for normal pregnancy." (PMID 34940120, 2021). "We conclude MMP-15 is up-regulated in preeclampsia, but does not cleave endoglin to produce soluble endoglin." (PMID 22768148, 2012).
acute myeloid leukemia (2 papers, 2020). Acute myeloid leukemia (AML) is a group of neoplasms arising from precursor cells committed to the myeloid cell-line differentiation. "MMP15 is high expressed in patients with acute myeloid leukemia (AML)." (PMID 32887509, 2020).
adenomyosis (2 papers, 2022 to 2025). The growth of endometrial tissue inside the muscular wall of the uterine corpus. "We analyzed MT2-MMP (MMP15) and MT3-MMP (MMP16) in eutopic endometrium with and without endometriosis and with and without adenomyosis and ectopic endometrium of deep infiltrating endometriosis (DIE), peritoneal endometriosis (PE), and ovarian endometriosis (Ov) by immunohistochemistry." (PMID 35453827, 2022).
COVID-19 (2 papers, 2021 to 2022). A disease caused by infection with severe acute respiratory syndrome coronavirus 2. "Although matrix metallopeptidase (MMPs) are proteolytic enzymes responsible for extracellular matrix protein degradation, in our study matrix metalloproteases such as MMP23B, MMP15 and MMP14 were downregulated in COVID-19 diseased lungs compared with expression in lungs of uninfected controls." (PMID 33674719, 2021). "However, the expression of the MMP-15 protein in COVID-19 was lower than in non-COVID-19 lung tissue." (PMID 35625532, 2022).
diabetes (2 papers, 2012 to 2022). "Finally, the group comprised of Mmp15 (matrix metallopeptidase 15), Rassf4 (ras association domain family member 4), Pfpl (pore forming protein-like), and Spi16 (serine protease inhibitor 16) responded to both diabetes and diet, in all combinations." (PMID 22701643, 2012).
glioma (2 papers, 2014 to 2020). A benign or malignant brain and spinal cord tumor that arises from glial cells (astrocytes, oligodendrocytes, ependymal cells). "The overlapping substrate panels of MT-MMPs, e.g., MMPs15, -16, and -24 are pro-MMP2 activators, suggest that these too might enhance the migration and infiltration of glioma cells; indeed, MMP15 and MMP16 have been demonstrated to enhance glioma cell migration in vitro." (PMID 32872536, 2020). "Possibly correlating with the very low RNA expression levels observed, MMP15 and MMP24 were not detectable by immunohistochemistry in glioma tissue." (PMID 32872536, 2020).
idiopathic pulmonary fibrosis (2 papers, 2017 to 2022). Idiopathic pulmonary fibrosis (IPF) is a nonneoplastic pulmonary disease that is characterized by the formation of scar tissue within the lungs in the absence of any known cause. "In the present study, it was observed that the ITC regulates the expression of the MMP-15 and TIMP-2 genes that have been recognized as inducers of pulmonary fibrosis." (PMID 29040281, 2017).
renal carcinoma (2 papers, 2023 to 2024). A carcinoma arising from the epithelium of the renal parenchyma or the renal pelvis. "However, our findings suggest that transmembrane metalloproteinase 14 (MMP-14) plays a much more significant and essential role than MMP-15 in the studied renal carcinoma tissues." (PMID 39125675, 2024). "MMP-14 appears to play a more significant role than MMP-15 in renal carcinoma, suggesting it could be a promising target for diagnosis, prognosis, and therapy in renal cell carcinoma." (PMID 39125675, 2024). "Even though the content of both investigated membrane-type metalloproteinases in renal cancer was similar, the activity of MMP-14 was much higher in both tumor phases compared to that of MMP-15." (PMID 39125675, 2024). "In renal cancer, AA suppressed cell migration and invasion by downregulating the mRNA and protein expression of MMP-15 (matrix metallopeptidase-15)." (PMID 37375849, 2023).
rheumatoid arthritis (2 papers, 2006 to 2022). A chronic, systemic autoimmune disorder characterized by inflammation in the synovial membranes and articular surfaces. "As previously reported, ZFAS1 depletion mitigates rheumatoid arthritis-like symptoms via miR-296-5p-dependent suppression of MMP-15." (PMID 36561842, 2022).
Arthritis (1 paper, 2022). Inflammation of a joint. "MMP15 and MMP17, as HUB genes, are involved in embryonic development, reproduction, and tissue damage recovery during normal physiological processes, however, they promote inflammation, such as arthritis and fibrosis, when the disease occurs." (PMID 35754546, 2022).
Crohn disease (1 paper, 2011). A gastrointestinal disorder characterized by chronic inflammation involving all layers of the intestinal wall, noncaseating granulomas affecting the intestinal wall and regional lymph nodes, and transmural fibrosis. "While the top ranked genes included some P/PIs previously found to be associated with CD and/or UC, such as MMP2, MMP15 and MST1, a series of P/PI genes were identified, which have not been previously related to Crohn's disease or ulcerative colitis." (PMID 21931648, 2011).
esophageal cancer (1 paper, 2020). A primary or metastatic malignant neoplasm involving the esophagus. "MMP15 positively correlates to the angiogenesis of human esophageal cancer." (PMID 32887509, 2020).
head and neck squamous cell carcinoma (1 paper, 2022). A squamous cell carcinoma that arises from any of the following anatomic sites: lip and oral cavity, nasal cavity, paranasal sinuses, pharynx, larynx, and salivary glands. "In murine model, TP63 loss led to activation of MAPK-P-STAT3 (Ser727)-MMP15 axis, resulting in metastatic spread of head and neck squamous cell carcinoma." (PMID 36936274, 2022).
kidney cancer (1 paper, 2024). Primary or metastatic malignant neoplasm involving the kidney. "However, MMP-14 demonstrated a much higher activity in both grades of kidney cancer, when compared to MMP-15." (PMID 39125675, 2024).
kidney tumor (1 paper, 2024). "We compared MMP-14 (membrane-type MMP 1) and MMP-15 (membrane-type MMP 2) in human kidney tumor to those in healthy parts of the same organ, which were used as a control material as ethical concerns excluded the possibility of taking a kidney sample from healthy donors." (PMID 39125675, 2024).
leukemia (1 paper, 2021). A malignant (clonal) hematologic disorder, involving hematopoietic stem cells and characterized by the presence of primitive or atypical myeloid or lymphoid cells in the bone marrow and the blood. "Its mammalian counterpart MMP15 (aka MT2-MMP) is apparently expressed in several myeloid cell lines and in AML samples, which suggests a contribution to the invasiveness properties of NA9-mediated leukemia." (PMID 34383740, 2021).
myeloma (1 paper, 2023). "This review focuses on the role of MMP-1, MMP-2, MMP-7, MMP-9, MMP-13, MMP-14, and MMP-15 and the four types of TIMPs in the invasion of myeloma cells, angiogenesis, osteolytic osteopathy, to offer some novel perspectives on the clinical diagnostics and therapeutics of MM." (PMID 37823051, 2023).
osteoarthritis (1 paper, 2025). A noninflammatory degenerative joint disease occurring chiefly in older persons, characterized by degeneration of the articular cartilage, hypertrophy of bone at the margins and changes in the synovial membrane. "Another member of the MMP family, MMP15, which has also been previously shown to be associated with osteoarthritis, showed increased gene expression in senescent cells." (PMID 40429909, 2025).
Osteochondrosis (1 paper, 2025). Abnormal growth ossification centers in children. "Dierks, using GWAS in Hanoverian warmblood horses, reported a QTL associated with osteochondrosis and osteochondrosis dissecans, which is the genomic region with MMP15 homology in the human genome." (PMID 41007912, 2025).
ovarian tumor (1 paper, 2014). "The induction of MMP15 (also known as membrane-type-2 MMP) has been shown to positively correlate with ovarian tumor metastases in murine xenographs." (PMID 24999452, 2014).
pilocytic astrocytoma (1 paper, 2020). Pilocytic astrocytoma is a rare subtype of low-grade glioma of the central nervous system characterized by a well circumscribed, often cystic, brain tumor with a discrete mural nodule and long, hair-like projections that extend from the neoplastic astrocytes. "Interestingly, pilocytic astrocytoma was the tumor type with the strongest upregulation of MMP15, -16, and -17, making this tumor the maximum overall MT-MMP expresser." (PMID 32872536, 2020).
proliferative diabetic retinopathy (1 paper, 2022). Advanced retinopathy due to diabetes mellitus characterized by the formation of new vessels in the retina. "We analyzed the expression of ADAMTS proteinases ADAMTS-1, -2, -4, -5 and -13; their activating enzyme MMP-15; and the degradation products of proteoglycan substrates versican and biglycan in an ocular microenvironment of proliferative diabetic retinopathy (PDR) patients." (PMID 36144730, 2022).
psoriasis plaques (1 paper, 2022). "However, MMP15 (MT2-MMP), which is present in the inflammatory dermatoses group but not normal skin, in the current study, is elevated in psoriasis plaques compared with peri-lesional skin." (PMID 35327667, 2022).
renal cell carcinoma (1 paper, 2024). "The highest actual MMP-15 activity (pkatals/kg of total protein content) was found in the grade G2 renal cell carcinoma samples." (PMID 39125675, 2024). "The aim of this study was to evaluate the expression, content, and activity of selected membrane-type metalloproteinases (MMP-14 and MMP-15) in human renal cell carcinoma." (PMID 39125675, 2024). "Therefore, the aim of this study was to evaluate the expression, content and activity of MMP-14 and MMP-15 in human renal cell carcinoma." (PMID 39125675, 2024). "Transmembrane metalloproteinases MMP-14, MMP-15 and MMP-16 have been found to be significantly expressed in tumor-transformed tissue in renal cell carcinoma and to be present in urine samples from the same patients; however, no reports have been published on their expression in renal cell carcinoma." (PMID 39125675, 2024).
squamous cell carcinoma (1 paper, 2011). A carcinoma arising from squamous epithelial cells. "Higher levels of MMP-15 are observed in nonsmall cell lung carcinomas (NSCLCs) relative to squamous cell carcinoma (SCCs) and normal lung tissues which indicate that MMP-15 may be a viable molecular diagnostic marker for NSCLCs." (PMID 21152183, 2011).
viral hepatitis (1 paper, 2023). An acute or chronic inflammation of the liver parenchyma caused by viruses. "On the contrary, other MMPs have a low level of expression such as MMP-1 in viral hepatitis and HCC, and MMP-15 during liver regeneration." (PMID 37509493, 2023).
tumor (41 papers, 2005 to 2025). "Silencing of LINC00482 also suppressed tumor-associated inflammation and angiogenesis in vivo, which was found to be reversed by the overexpression of MMP15." (PMID 33323547, 2020). "MMP15 is a membrane-type peptidase that has been associated with angiogenesis and epithelial-mesenchymal transition in tumor progression." (PMID 32992998, 2020). "We also presented the underlying mechanisms of HLA-G in tumor progression not only related to the inhibition of NK lysis, but to the specific induction of matrix metalloproteinase-15 (MMP-15) expression." (PMID 30234020, 2018). "This role for MMPs in tumor pathophysiology also makes them a potential therapeutic target, and high levels of MMP2, MMP9, MMP15, MMP16 have been shown to be expressed in GBM tumor cells and associated with poor prognoses." (PMID 41400763, 2025). "Such progress in tumor invasiveness from tumor grade G2 to G3 involved a significant decrease in the MMP-15 content." (PMID 39125675, 2024). "Based on the results, it can be concluded that MMP-14 is significantly less active in tumor tissue than in control tissue; at the same time, it is also approximately 70 times more active in healthy human kidney samples than MMP-15." (PMID 39125675, 2024). "The G3 tumor samples demonstrated the highest specific activity of MMP-15—approximately 1.8 times higher than in the respective control sample and over 22% higher than in the G2 tumor samples." (PMID 39125675, 2024). "The new model included five variables: tumor size, neural invasion, lymphovascular invasion, cytoplasmic MMP15 expression, and the number of positive SLNs." (PMID 36035312, 2022). "Tumor size, neural invasion, lymphovascular invasion, MMP15 expression in the cytoplasm, and the number of positive SLNs were statistically significant in multivariate regression analysis (P < 0.05) and independent risk factors for NSLN metastasis." (PMID 36035312, 2022). "MMP15 can affect the tumor microenvironment by degrading the extracellular matrix and affecting signal transduction by interacting with growth factors." (PMID 36035312, 2022). "The new model included five variables (tumor size, number of positive SLNs, lymphovascular invasion, neural invasion, and MMP15 expression in the cytoplasm)." (PMID 36035312, 2022). "During progression of cancer, downregulation of MMP15 expression exerted inhibitory functions in tumor growth." (PMID 33323547, 2020). "The growth of the tumor significantly slowed down after the injection with cells expressing sh-MMP15, whereas it was found to be accelerated following the treatment with oe-MMP15 (p < 0.05)." (PMID 33323547, 2020). "And CXCR4 positive cells increased expression of MMP9 and MMP15, which are known to play an important role in extracellular matrix remodeling during the process of tumor invasion and metastasis." (PMID 32232002, 2020). "Several studies suggest that MMP15 acts as a critically intermediate regulator, and then contributes to tumor progression." (PMID 32887509, 2020). "The same group showed that HLA-G not only impairs NK cells, but it also triggers tumor metastasis via the up-regulation of MMP15." (PMID 26460949, 2015). "MMP-15 and -19 expression was clearly restricted to the cytoplasm of tumor cells using immunocytochemistry." (PMID 19531263, 2009). "MMP-15 showed a strong staining in the cytoplasm of tumor cells with additional slightly staining of few stromal cells and in some nuclei of tumor cells." (PMID 19531263, 2009). "The G2 and G3 tumor samples contained smaller amounts of MMP-15." (PMID 39125675, 2024). "In addition, a significantly higher specific activity of MMP-14 in tumor tissue was determined, compared to MMP-15." (PMID 39125675, 2024). "Tumor size, neural invasion, lymphovascular invasion, expression of matrix metalloproteinase 15 (MMP15) in the cytoplasm, and the number of positive SLNs were statistically significant by multivariate analysis (P < 0.05), which were used to establish the new model." (PMID 36035312, 2022).